NFKBIZ (NFKB inhibitor zeta)
Description:
Involved in regulation of NF-kappa-B transcription factor complexes. Inhibits NF-kappa-B activity without affecting its nuclear translocation upon stimulation. Inhibits DNA-binding of RELA and NFKB1/p50, and of the NF-kappa-B p65-p50 heterodimer and the NF-kappa-B p50-p50 homodimer. Also seems to activate NF-kappa-B-mediated transcription. In vitro, upon association with NFKB1/p50 has transcriptional activation activity and, together with NFKB1/p50 and RELA, is recruited to LCN2 promoters. Promotes transcription of LCN2 and DEFB4. Is recruited to IL-6 promoters and activates IL-6 but decreases TNF production in response to LPS (By similarity). Seems to be involved in the induction of inflammatory genes activated through TLR/IL-1 receptor signaling (By similarity). Involved in the induction of T helper 17 cells (Th17) differentiation upon recognition of antigen by T cell antigen receptor (TCR) (By similarity).
Synonyms: IkB-zeta; IkappaBzeta; INAP; MAIL; IKBZ; FLJ34463; I-kappa-B-zeta; IkappaB-zeta
Tractability: Small molecule: a structure with a bound ligand is known. PROTAC: ubiquitination databases record sites on it.
Gene: Protein-coding gene on chromosome 3 (101,827,991 to 101,861,022, forward strand). Ensembl gene ENSG00000144802.
Subcellular location: Nucleus
Subcellular location (Human Protein Atlas): Nuclear speckles; Cytoplasmic bodies
Gene Ontology:
Molecular function: protein binding; cis-regulatory region sequence-specific DNA binding; DNA binding; POU domain binding; RNA polymerase II cis-regulatory region sequence-specific DNA binding; transcription coregulator activity
Biological process: positive regulation of inflammatory response; positive regulation of T-helper 17 cell differentiation; regulation of gene expression; T cell receptor signaling pathway; adaptive immune response; B cell proliferation; B cell receptor apoptotic signaling pathway; B cell receptor signaling pathway; cellular response to cytokine stimulus; cellular response to interleukin-17; cellular response to lipopolysaccharide; cellular response to transforming growth factor beta stimulus; chromatin organization; chromatin remodeling; chronic inflammatory response; cytokine-mediated signaling pathway; defense response to Gram-negative bacterium; defense response to virus; epithelial cell apoptotic process; establishment of skin barrier; execution phase of apoptosis; gene expression; homeostasis of number of cells within a tissue; immunoglobulin mediated immune response; inflammatory response to wounding; and 32 more
Cellular component: nuclear speck; nucleus
Genetic constraint (gnomAD): Loss-of-function variants: 18 observed, 70.22 expected, observed/expected ratio (o/e) 0.26, 90% interval 0.18 to 0.38. The upper end of that interval is the gene's LOEUF score, 0.38, which puts it in group 1 of 6, group 1 being the genes least tolerant of losing a copy. Missense variants: 813 observed, 868.58 expected, observed/expected ratio (o/e) 0.94, 90% interval 0.88 to 0.99. Synonymous variants: 362 observed, 333.86 expected, observed/expected ratio (o/e) 1.08, 90% interval 0.99 to 1.18.
Gene-disease validity (ClinGen):
ClinGen rates the evidence that NFKBIZ causes each of these diseases.
hereditary nonpolyposis colon cancer (autosomal dominant): Limited.
Homologues: Orthologues: chimpanzee NFKBIZ (99% identical), pig NFKBIZ (87% identical), macaque NXPE3 (86% identical), rabbit NFKBIZ (85% identical), guinea pig NFKBIZ (85% identical), dog NFKBIZ (83% identical), rat Nfkbiz (81% identical), mouse Nfkbiz (70% identical), tropical clawed frog nfkbiz (50% identical), zebrafish nfkbiz (35% identical). Paralogues in human: NFKBID (21% identical), ANKRA2 (9% identical), RFXANK (8% identical).
Diseases named in the same sentence as NFKBIZ in open-access papers:
NFKBIZ is named in the same sentence as 65 diseases in open-access papers, as found by Europe PMC text mining. Sharing a sentence is not in itself a finding about the gene and the disease. The quoted sentences say what the papers report.
psoriasis (11 papers, 2019 to 2024). An autoimmune condition characterized by red, well-delineated plaques with silvery scales that are usually on the extensor surfaces and scalp. "NFKBIZ is a psoriasis susceptibility gene that encodes the functions of TRAF6 signalling players, especially in terms of positive and regulatory immune controls by interactions between immune cells and epithelial cells." (PMID 36925653, 2023). "While the protein product of NFKBIZ, IκBζ, can inhibit the activity of NF-κB, it can also activate the transcription of a set of genes associated with the overactivation of the immune system in psoriasis." (PMID 35977489, 2022). "Studies on diseases with autoimmune and inflammatory disorder such as psoriasis, Crohn’s disease, and ulcerative colitis shed light on the pivotal effects NFKBIZ exerted." (PMID 38581570, 2024). "There are 122 differentially upregulated and 210 differentially downregulated genes in common between the activated + fisetin and the activated group alone, notably many psoriasis-associated genes such as CCL20, IL36G, IL23A and NFKBIZ." (PMID 36741386, 2022). "The expression of NFKBIZ (a nuclear inhibitor of NF-κB) in keratinocytes has been found to trigger not only skin lesions but also systemic inflammation in mouse psoriasis models." (PMID 36699407, 2022). "We identified IL-17 as the main Th17 cell derived cytokine that induced upregulation of the genes encoding NF-kappa-B inhibitor zeta (NFKBIZ) and psoriasis-associated mediators, including CCL20, IL36G, and the antimicrobial peptide human β Defensin 2 (DEFB4A)." (PMID 30972071, 2019). "On the other hand, patient 2 and 3 shared SNPs in NFKBIZ and in TNFAIP3, encoding the IL-17/TRAF6 signaling regulators IKB-ζ and A20, respectively, whose genetic variability could contribute to immune dysregulation and chronic inflammation in psoriasis lesions." (PMID 38495872, 2024).
ulcerative colitis (6 papers, 2021 to 2024). An inflammatory bowel disease involving the mucosal surface of the large intestine and rectum. "NFKBIZ mutations are very common in the epithelium of patients with ulcerative colitis but are rarely found in sporadic or colitis-related cancers, suggesting the selection of NFKBIZ-mutant cells during colorectal carcinogenesis." (PMID 37377955, 2023). "NFKBIZ mutation is associated with ulcerative colitis, and the repeated inflammation and repair are closely related to the occurrence of colorectal cancer." (PMID 33708242, 2021). "Notably, the mutation rate of NFKBIZ was higher in intestinal epithelial cells in the context of ulcerative colitis, but lower in colitis-led tumor cells, suggesting that intestinal epithelial cells may resist tumor transformation through selective NFKBIZ mutation." (PMID 38581570, 2024). "An interest in better understanding the close collaboration between p50 and IκBζ is heightened by the frequent relationship between NFKBIZ and human diseases, including cancer and ulcerative colitis." (PMID 38918046, 2024). "In the ulcerative colitis (UC) patient data, in accordance with previous literature, NFKBIZ was upregulated in UC patients and even more in active UC cases, whereas we could show that DLG2 was downregulated." (PMID 35499706, 2022). "To explore CRISPR-Select modeling of a noncancer disease, we tested loss-of-function variants in NFKBIZ in the IL-17A signaling pathway, which have been identified in ulcerative colitis colon epithelium and shown to confer survival advantage to colon epithelial organoids." (PMID 36471068, 2022).
colitis (5 papers, 2022 to 2024). Inflammation of the colon. "Moreover, NFKBIZ (also known as IκBζ) gene mutations were abundant in colitis samples, but the incidence and severity of colorectal tumors decreased significantly in NFKBIZ-deficient mice." (PMID 37875976, 2023). "There is clear evidence of strong positive selection for NFKBIZ mutations in the colonic epithelium, and a NFKBIZ mutation clone can expand to encompass a substantial fraction of the tissue specifically in individuals with colitis." (PMID 35726685, 2022).
colon carcinoma (5 papers, 2021 to 2023). "Previous reports identified mutations in NFKBIZ in colon cancer which disrupt a stop codon, producing an abnormally long C-terminal region." (PMID 35499706, 2022). "IL-16 plays a role in promoting cellular inflammation; BCl-6 plays a role in inhibiting apoptosis in colon cancer cells; and NFKBIZ plays a role in promoting the expression of the IL-17 inflammatory signaling pathway." (PMID 36839472, 2023). "In light of the building body of evidence that DLG2 is an important tumor suppressor gene we here investigate DLG2 and NFKBIZ and their impact on the inflammasome induction in inflammatory colon disease and in colon cancer." (PMID 35499706, 2022). "Notably, cells with NFKBIZ mutations are almost never found in colon cancers, and mice with NFKBIZ genetic disruption are resistant to the induction of colon adenocarcinomas, indicating that such expansions impede carcinogenesis." (PMID 35726685, 2022).
acute kidney injury (4 papers, 2020 to 2025). Sudden and sustained deterioration of the kidney function characterized by decreased glomerular filtration rate, increased serum creatinine or oliguria. "Interestingly, dysregulated NFKBIZ (sometimes also called IKBZ or INAP) signaling is associated with acute kidney injury and associated immune response." (PMID 39777909, 2025). "In detail, miR‐376b and miR‐124a can inhibit NFKBIZ expression, while miR‐376b and Nfkbiz have an impact on liver regeneration, tubular damage, and intrarenal inflammation in acute kidney injury." (PMID 40359334, 2025). "Kidney injury: NFKBIZ is a hub gene in acute kidney injury (AKI) according to a bioinformatics-based study." (PMID 37377955, 2023).
colorectal cancer (4 papers, 2019 to 2025). A primary or metastatic malignant neoplasm that affects the colon or rectum. "Included within the upregulated genes in the concurrent mutation group were some previously linked with colorectal cancer carcinogenesis, including NFKBIZ, CCL20, LCN2, PLOD2, MUC1, and MUC4." (PMID 40757636, 2025). "However, a downregulation in NFKBIZ was seen in the paired tumor tissue compared to healthy mucosa from colorectal cancer patients (log2 FC = 0.52, p < 0.001)." (PMID 35499706, 2022).
lymphoma (4 papers, 2018 to 2023). A malignant (clonal) proliferation of B- lymphocytes or T- lymphocytes which involves the lymph nodes, bone marrow and/or extranodal sites. "NFκB pathway activation is a feature of many lymphomas, and NFKBIZ expression is a key hallmark of the activated subtype of DLBCL in humans, which is similar to the most common form in dogs." (PMID 38133254, 2023). "Furthermore, when examining AI of somatic mutations, NFKBIZ showed one of the highest frequencies of imbalance (21/33 patients, 64%) compared to other lymphoma-associated genes." (PMID 30275490, 2018). "Here, we independently confirmed high NFKBIZ expression in MyD88L265P lymphoma cells and identified NFKBIZ as one of the top genes upregulated by MyD88L265P oncogenic NF-κB signaling." (PMID 36982699, 2023). "Recurrent somatic events were identified in the 3′ UTRs of TOB1 (carcinoma and pan-cancer meta-cohorts), NFKBIZ (lymphomas) and ALB (liver cancer)." (PMID 32025015, 2020). "Several studies have suggested that NFKBIZ may be a driver gene for the development and progression of certain types of cancer, including lymphoma." (PMID 36982699, 2023). "In normal B cells, NFKBIZ expression is induced by BCR or TLR stimulation and an increase in the NFKBIZ transcript and IκBζ protein was demonstrated due to constitutive oncogenic NF-κB signaling in MyD88L265P- or CARD11L244P-expressing lymphoma cells." (PMID 36982699, 2023).
rectal cancer (4 papers, 2019 to 2024). A primary or metastatic malignant neoplasm that affects the rectum. "Studies on rectal cancer showed that NFKBIZ mutations were associated with rectal cancer radiation resistance." (PMID 38581570, 2024). "NFKBIZ is a highly mutated genes in rectal cancer, and mutations in NFKBIZ have been associated with chemoradiotherapy (CRT) resistance." (PMID 37377955, 2023). "Additionally, it has garnered significant attention over past years that NFKBIZ plays an important role in the tumorigenesis of many diseases, such bladder cancer, rectal cancer and DLBCL." (PMID 38581570, 2024).
bladder cancer (3 papers, 2022 to 2024). "The PI3K/AKT pathway is also overactivated in bladder cancer, promoting cell proliferation, survival, and metastasis, and the NF-kB pathway inhibitor (NFKBIZ) can inhibit tumor cell proliferation through the PTEN/PI3K/Akt signaling pathway." (PMID 38419066, 2024). "Relative research of bladder cancer showed NFKBIZ exerted an antitumoral effect by modulating PTEN/PI3K/Akt signaling pathway." (PMID 38581570, 2024). "Furthermore, NFKBIZ has been shown to be downregulated in bladder cancer and to affect the PI3K/AKT/mTOR pathway to inhibit proliferation." (PMID 35499706, 2022).
glioblastoma (3 papers, 2016 to 2024). The most malignant astrocytic tumor (WHO grade IV). "The tumor-suppressor miR-124a, and miR-223, which target the NFKBIZ mRNA, were recently shown to be silenced in glioblastomas, and we have observed that IκBζ is expressed in these glial tumors where it prevents spontaneous cell death (unpublished data)." (PMID 27579619, 2016). "Lou demonstrated that the NF-kB inhibitor zeta (NFKBIZ) was a downstream target of NUDT21, and that MES recognition genes CHI3L1 and FN1 were differentially regulated in glioblastoma cells." (PMID 38349866, 2024).
mastitis (3 papers, 2018 to 2023). Inflammation of breast tissue during lactation or postpartum due to an obstructed duct or infection. "For example, NFKBIZ is a regulator of NF-kappaB and gene variants of this gene is introduced as potential markers of mastitis resistance in dairy heifers." (PMID 32754201, 2020). "Investigations have revealed that function and gene polymorphisms of NFKBIZ can be introduced as potential markers of mastitis resistance in dairy heifers." (PMID 29470489, 2018). "NFKBIZ is a key regulator of the NF-κB inflammation pathway considered to be critical for mastitis pathogenesis." (PMID 37420291, 2023). "Some of the highly connected genes in the purple module have previously been related to mastitis development including NFKBIZ, NFKBIA, CXCL2, GRO1, CXCL3, LPIN1, and DAB2." (PMID 32754201, 2020).
B-Cell Lymphoma (2 papers, 2022 to 2023). "Moreover, its overexpression has been implicated in cell viability and chemoresistance in B-cell lymphomas; however, no data were available on NFKBIZ in RCC." (PMID 35814450, 2022).
Coronary Artery Disease (2 papers, 2019 to 2025). "We have recently demonstrated that NFKB1 variation was an independent risk factor for developing type 2 diabetes, while the NFKBIZ variant was an independent risk factor for developing early-onset coronary artery disease." (PMID 31815120, 2019).
COVID-19 (2 papers, 2022 to 2023). A disease caused by infection with severe acute respiratory syndrome coronavirus 2. "Two of the loci described herein—the ABO cluster that associates with CDTA and the PA locus closest to the gene NFKBIZ—have been implicated with COVID-19 severity." (PMID 36653354, 2023). "Some examples include IL10, a tolerogenic cytokine whose expression is increased in COVID-19, and NFKBIz, whose level of expression is decreased." (PMID 36443794, 2022).
Crohn disease (2 papers, 2024 to 2025). A gastrointestinal disorder characterized by chronic inflammation involving all layers of the intestinal wall, noncaseating granulomas affecting the intestinal wall and regional lymph nodes, and transmural fibrosis. "For example, TLR7, NFKBIA, NFKBIZ, NFKB2, and TNFRSF19 have been shown to be upregulated in epithelial cells and macrophages during infection with AIEC strains isolated from Crohn’s disease patients." (PMID 40572318, 2025).
dermatitis (2 papers, 2017 to 2024). An inflammatory process affecting the skin. "This loop is further amplified by IL-17C–TCF4 autocrine regulation of ZC3H12A and IL-17C regulation of NFKBIZ to promote self-sustaining skin inflammation." (PMID 38470486, 2024). "A negative TCF4/IL-17C/ TNF-a/ IL-17A feedback loop decreases TCF4 in an IL-17RA/RE-dependent manner and is further amplified by IL-17C/TCF4 regulation of ZC3H12A and IL-17C regulation of NFKBIZ, resulting in self-sustaining skin inflammation." (PMID 38470486, 2024).
glial tumors (2 papers, 2016 to 2017). "Cell proliferation assay indicated that NFKBIZ silencing could reverse the effect of NUDT21 in human glioma, and NF-κB nuclear translocation induced by LPS could also reverse the anticancer effect of NUDT21 knockdown." (PMID 29311812, 2017).
inflammatory bowel disease (2 papers, 2017 to 2022). A spectrum of small and large bowel inflammatory diseases of unknown etiology. "Several IEC signature TFs have known associations with human Inflammatory Bowel Diseases (IBD), including SMAD7, CEBPG, STAT3, XBP1, HNF4A, ELF3, IRF1, and NFκB components IKBKB, IKBKG, and NFKBIZ." (PMID 28850571, 2017).
Arthritis (1 paper, 2013). Inflammation of a joint. "Interestingly, studies demonstrated that NFKBIZ mediated IL-6 production, ADRB2 antagonists reduced the severity of arthritis, and that anti-CXCL16 antibody inhibited infiltration of inflammatory cells and arthritis." (PMID 23936839, 2013).
asthma (1 paper, 2020). "NFKBIZ has been previously associated with amygdala reactivity, drug abuse, and in GWAS of asthma." (PMID 32381021, 2020).
autism (1 paper, 2009). Persistent deficits in social interaction and communication and interaction as well as a markedly restricted repertoire of activity and interest as well as repetitive patterns of behavior. "Thus, the elevation of NFKBIZ in peripheral cells derived from autistic probands may be a reflection of a systems-wide activation of the innate immune system in autism, providing strong support for the use of LCL as a surrogate model to examine gene dysregulation in ASD." (PMID 19492049, 2009).
chronic pancreatitis (1 paper, 2010). A chronic inflammatory process causing damage and fibrosis of the pancreatic parenchyma. "Given the prevalence of chronic pancreatitis and high degree of stromal fibrosis, it is possible that NFKBIZ may play a role in PDAC and inflammation." (PMID 20644708, 2010).